SH3TC1 (SH3 domain and tetratricopeptide repeats 1)
Synonyms: FLJ20356
Tractability: PROTAC: ubiquitination databases record sites on it; its protein half-life has been measured.
Gene: Protein-coding gene on chromosome 4 (8,182,072 to 8,241,803, forward strand). Ensembl gene ENSG00000125089.
Subcellular location (Human Protein Atlas): Nucleoli; Nucleoli rim; Cytosol; Nucleoplasm
Genetic constraint (gnomAD): Loss-of-function variants: 132 observed, 107.21 expected, observed/expected ratio (o/e) 1.23, 90% interval 1.07 to 1.42. The upper end of that interval is the gene's LOEUF score, 1.42, which puts it in group 5 of 6, group 1 being the genes least tolerant of losing a copy. Missense variants: 1,915 observed, 1,614 expected, observed/expected ratio (o/e) 1.19, 90% interval 1.14 to 1.23. Synonymous variants: 823 observed, 736.71 expected, observed/expected ratio (o/e) 1.12, 90% interval 1.05 to 1.18.
Homologues: Orthologues: chimpanzee SH3TC1 (99% identical), macaque SH3TC1 (94% identical), dog SH3TC1 (77% identical), pig SH3TC1 (75% identical), mouse Sh3tc1 (73% identical), rat Sh3tc1 (73% identical), guinea pig SH3TC1 (70% identical), tropical clawed frog sh3tc1 (48% identical), zebrafish SH3TC1 (39% identical). Paralogues in human: SH3TC2 (34% identical).
Diseases named in the same sentence as SH3TC1 in open-access papers:
SH3TC1 is named in the same sentence as 6 diseases in open-access papers, as found by Europe PMC text mining. Sharing a sentence is not in itself a finding about the gene and the disease. The quoted sentences say what the papers report.
diabetes mellitus (1 paper, 2022). A metabolic disorder characterized by abnormally high blood sugar levels due to diminished production of insulin or insulin resistance/desensitization. "Since these are mainly early-onset strokes, the same study showed that higher blood pressure levels were found in subjects with polymorphisms of these genes, while the polymorphisms of other genes, CSN3, HLA-DPB1 and SH3TC1, are associated with cardiovascular diseases and diabetes mellitus." (PMID 35741740, 2022).
SH3TC1 also shares sentences with these, for which no sentence is quoted: allergic disease (1 paper); asthma (1); cancer (1); cardiovascular diseases (1); Stroke (1).